ACHE (acetylcholinesterase (Yt blood group))
Diseases named in the same sentence as ACHE in open-access papers (continued):
Sharing a sentence is not in itself a finding about the gene and the disease.
amnesia (continued). "In the present study, the capability of DL0410 in ameliorating the amnesia induced by scopolamine was investigated, and its effect on the cholinergic system in the hippocampus and its binding mode in the active site of AChE was also explored." (PMID 28272324, 2017). "All of the evidence indicated that its AChE inhibition is an important mechanism in the anti-amnesia effect." (PMID 28272324, 2017). "Increased AChE levels were also found in the brain of neurodegenerative transgenic mice with impaired memory, supporting our result of elevated AChE levels during scopolamine induced amnesia." (PMID 26413129, 2015). "The dysfunction of central cholinergic neuronal systems, including decreased brain acetylcholine levels and an up-regulation of AChE activity, has been shown to be related to the degrees of amnesia and Aβ deposition in AD brain." (PMID 24968859, 2014). "The potential neuroprotective effects of the NAF are linked to inhibition of AChE and MDA production in mice brain tissue with Aβ-induced amnesia." (PMID 25496367, 2014). "Disruption of synaptic plasticity is commonly observed in both amnesia and AD; however, it may be reversible through the action of chlorogenic acid, which exerts its effects via anti-AChE and anti-oxidative activities." (PMID 40429757, 2025). "Bisuracil 2b demonstrated significant prophylactic potential against OP poisoning by protecting AChE from irreversible inhibition by POX, while bisuracil 3c effectively inhibited brain AChE activity in vivo to improve memory deficits in a scopolamine-induced amnesia model in mice." (PMID 40332440, 2025). "In addition, ellagitannins such as tellimagradin I purified from Trapa taiwanensis Nakai hulls showed AChE inhibitory activities in scopolamine-induced amnesia mice." (PMID 36014555, 2022). "Similarly, lycopene was shown to ameliorate Scopolamine-induced amnesia by lowering the activity of AchE in mice." (PMID 34294819, 2021). "Furthermore, our previous experiments revealed that xanthotoxin, administered subchronically at the dose of 1 mg/kg, decreased the level of AChE in the scopolamine-induced amnesia model in mice." (PMID 33579030, 2021). "The scopolamine-induced amnesia could also enhance the AChE activity and oxidative stress in the brain extracts." (PMID 34440270, 2021). "Scopolamine has been shown to induce amnesia by competitively binding with acetylcholine at muscarinic receptors, and this phenomenon could be recovered by AChE inhibitors." (PMID 34440270, 2021). "Therefore, the amnesia model induced by scopolamine is generally used to investigate AChE inhibitors and their effects on AD management." (PMID 34440270, 2021). "Multiple-dose injection of Z. multiflora extract could dose-dependently inhibit acetylcholinesterase (AchE) in the brain hippocampus of scopolamine-induced amnesia rats." (PMID 33927634, 2021). "In addition, chlorogenic acid ameliorates the scopolamine-induced amnesia in mice by anti-AChE and antioxidant activities." (PMID 31046739, 2019). "Therefore, protecting cholinergic system from functional degeneration and sustaining the normal activity of ChAT and AChE might be serviceable against SCOP-induced amnesia." (PMID 27556046, 2016). "Additionally, the mechanism underlying the reversal of SC-induced amnesia by the saponin-rich EP extract remains to be fully elucidated but is not related to the inhibition of AChE and BuChE activity." (PMID 26483842, 2015). "There were promising neuroprotective outcomesand cognitive enhancement after scopolamine-induced amnesia, where EEPD suppressedthe AChE enzyme in mice brain at two doses (200 and 400 mg/kg)." (PMID 39504064, 2024). "As a dual inhibitor of AChE and BuChE, the in vivo effect of DL0410 has been verified in a series of AD-related mouse models, including Aβ1-42-induced amnesia in mice and APP/PS1 transgenic mice." (PMID 28272324, 2017).
amnesia (continued). "Limonene present in the essential oil mixture (MO: 1% and 3%) has been known to revert cognitive deficits in the scopolamine-induced amnesia rat model by alleviating the oxidative stress markers (MDA, SOD, GSH) and inhibiting AChE (24.9%) and BchE (69.1%; IC50, 1.096 ± 0.043 μg/mL) activities." (PMID 36432418, 2022). "In addition to its inhibition of AChE activity in vitro, the ameliorating effect of DL0410 on scopolamine-induced amnesia (a specific model mimicking changes in the cholinergic system) via the inhibition of AChE has been verified." (PMID 29276489, 2017). "In the scopolamine-induced amnesia mouse model, we found that AChE activity in the model group was significantly increased compared with the control group, which was consistent with the literature, and DL0410 (3 mg/kg, 10 mg/kg, and 30 mg/kg) suppressed AChE significantly." (PMID 28272324, 2017). "However, literatures on the effects of the Bacopa monnieri extract particularly the CDRI-8 on alterations in the AChE activity and its possible correlation with expression of the NMDA receptor subunit GluN2B especially in various brain regions in animal models of experimental amnesia are lacking." (PMID 26413117, 2015).
depression (44 papers, 2012 to 2026). "A significant increase in AChE activity in the brains of mice with depression phenotypes and a positive correlation between AChE and O2•− levels associated with depressive behaviors have been demonstrated." (PMID 40225229, 2025). "Most of the farmers included in the study reported two or more clinical symptoms which were associated significantly with the depression of AChE enzyme activity." (PMID 37252928, 2023). "A similar study also examined a group of 529 adolescents in agricultural regions and found an association between decreased AChE activity and the onset of depression in adolescents, particularly in adolescent girls." (PMID 34502198, 2021). "The association between DNA damage and AChE depression was much stronger, indicating that assessment of internal exposures may better predict biological outcomes than monitoring of external exposures." (PMID 39220725, 2024). "However, the significantly lowered AchE activity occurred in the hippocampus area, but reserpine caused significant increases in AChE activity in the cortex and striatum in the depression rat model." (PMID 35705968, 2022). "Moreover, both washing the equipment after pesticide application and keeping pesticide products at home were significantly associated with the frequency of AChE depression." (PMID 35017597, 2022). "Decreased AChE activity is associated with a risk of developing depression." (PMID 35705968, 2022). "In addition, studies should be directed towards understanding the cause of the differential response to AChE inhibitors in depressive disorders." (PMID 34502198, 2021). "There was upregulation in the MAO and AchE activity and attenuation in the Na+/K+-ATPase in the cortex and hippocampus of the rat model of depression." (PMID 40522360, 2025). "In the rat model of depression induced by reserpine, a significant increase was observed in the activity of both AchE (p = 0.016, p = 0.033) and MAO (p = 0.001, p = 0.007) in the cortex and hippocampus respectively." (PMID 40522360, 2025). "AChE inhibitors are principal drugs prescribed to alleviate symptoms in AD patients, while up to 50% of these individuals also suffer from depression, frequently treated with selective serotonin reuptake inhibitors (SSRIs)." (PMID 40733311, 2025). "Still, the dual ability of the leaf extract from O. europaea Madural to inhibit AChE and MAOs surges as an interesting natural target for designing innovative pharmacological solutions to address AD and PD, or even depression." (PMID 38543060, 2024). "A prospective cohort study in an Ecuadorian agricultural community saw an increase in adolescent (11–17 years) depression symptoms as AChE activity decreased, a relationship that was strongest at older ages and among female participants." (PMID 38098750, 2023). "Both pharmacological and molecular genetic decreases in hippocampal AChE activity increase depression-like behaviors that is sensitive to FLX treatment." (PMID 33679340, 2021). "The use of AChE inhibitors in the treatment of depressive disorders such as MDD, LOD or BPAD has many limitations." (PMID 34502198, 2021). "AChE also plays a role in the theory of catecholaminergic–cholinergic balance in depressive disorders." (PMID 34502198, 2021). "AChE is reported to be depressed in depression, and some other neurological disorders and is known to interact with many drugs of abuse." (PMID 32414087, 2020). "Symptoms of depression can be induced in humans through blockade of acetylcholinesterase (AChE) whereas antidepressant-like effects can be produced in animal models and some clinical trials by limiting activity of acetylcholine (ACh) receptors." (PMID 31652614, 2019). "In conclusion, postnatal CPF had long-term effects on fear and depression, as well as on expression of AChE mRNA." (PMID 25972795, 2015).
depression (continued). "The cholinergic system has also been implicated in acute stress with inhibitors of the acetylcholine-hydrolyzing enzyme acetylcholinesterase (AChE) producing symptoms of depression and cognitive decline in mice via potentiation of acetylcholine signaling." (PMID 23805071, 2013). "Of note, the discrepancies in the effect of IPD, CPS, and IPD + CPS exposure on depression, despite their similar inhibitory effect on AChE, could be related to their different modulatory effect on other neurotransmitters." (PMID 37235246, 2023). "Finally, docking studies suggest potential future applications of the MTDL 3c in complex diseases such as major depression and AD, which involve targeting AChE and/or BChE enzymes and melatonin MT1 and MT2 receptors." (PMID 37765003, 2023). "The IPD-induced depression could be related to the decreased AChE activity." (PMID 37235246, 2023). "In addition, it was reported that decreases in AChE activity could increase depression-like behaviors." (PMID 36078631, 2022). "Moreover, in lipopolysaccharides (LPS)-induced depression, decreased AChE activity was demonstrated and it was suggested that these changes may be involved in depression complications." (PMID 34502198, 2021). "The variable clinical outcomes may reflect the fact that, by increasing synaptic levels of acetylcholine, AChE inhibitors increase stimulation of both muscarinic and nicotinic acetylcholine receptors, and these two receptors may be differentially involved in depression." (PMID 26769042, 2016). "In addition, a recent study in mice found that anxiety and depression behaviors elicited through administration of physostigmine, an inhibitor of AChE could be reversed with administration of nicotinic and muscarinic receptor antagonists." (PMID 23805071, 2013). "-Inhibition of scopolamine-induced increases in AChE and GSH.-Sustained release of frankincense by the incorporation of Lf, with a release rate of 18.2% after 48 h.-Alleviation of depression and stress by F-PMBN-Lf.-Improvements in short-term memory." (PMID 39728554, 2024). "The inhibition of BACE1, AChE, and BChE, in AD, hMAO-B in PD, and MAO-A in depression was performed efficiently by SPs, glycoproteins, carotenoids, especially fucoxanthin, and phlorotannins." (PMID 35736165, 2022). "Important genes involved in neurotransmitter transmission in these pathways include ACHE, MAOA, and DRD2 are related to the development of depression." (PMID 36072347, 2022). "On the other hand, treatment of reserpine model of depression with HPS-NPs and QUR-NPs restored the cortical and hippocampal changes in the enzymatic activities to control-like values except for AChE activity, which remained affected after QUR-NPs treatment in the cortical tissue." (PMID 40522360, 2025). "Given its higher capacity to inhibit both AChE, BuChE, and MAO-A, O. europaea Madural’s leaf extract may be proposed as a natural multitarget treatment for AD, PD, and depression." (PMID 38543060, 2024). "Thus, the potent antioxidant and inflammatory properties and the inhibition of AChE may be involved in the antidepressant activities of the species H. cotinifolia, which would be positioned as a candidate for study in drug development as an alternative in the treatment of depression." (PMID 38999004, 2024). "In the present study, there was no indication of such depression, which explains the relationship between symptoms and AChE, even if the proportion of the participants with depressed numbers was observed to be higher than those who were above the limit." (PMID 30835378, 2018). "Currently, due to the limited efficacy of AChE inhibitors as standalone treatments, there is a growing demand for new therapeutic options to address this condition as well as a lack of alternative treatment options for patients with depression." (PMID 40733311, 2025).
depression (continued). "There is a hypothesis that the depression observed in patients with AD treated with AChE inhibitors is a side effect of the therapy and not a comorbidity." (PMID 36499171, 2022).
neuroblastoma (34 papers, 2008 to 2025). Neuroblastoma (NB) is the most common solid, extracranial childhood tumor. "Surface flow cytometric analyses indicated that BChE, α7 AChR, and M1 AChR were present at the cell surface of SH-SY5Y neuroblastoma cells, while only minimal levels of AChE were detected extracellularly or at the cell surface." (PMID 41226363, 2025). "Our study proved that exposure to Al affected some biological processes, including loss of neurons viability, lipid peroxidation, and an increase of AChE activity in the neuroblastoma cell line SH-SY5Y." (PMID 38383833, 2024). "Petrosamine proved to be a safe, potent inhibitor of AChE against AlCl3-induced neurotoxicity in the neuroblastoma cell line SH-SY5Y and zebrafish embryos making this study a step forward in evaluating the translational value of this marine-derived alkaloid." (PMID 38383833, 2024). "We have also explored in vitro anti-AChE, anti-oxidant, anti-amyloids, and neuroprotective potential of O. dioica Roxb leaves extract using neuroblastoma (SHSY-5Y) cells." (PMID 37234712, 2023). "It is important to emphasize that based on neuroblastoma observations, Johnson and collaborators proposed that the molecular forms of AChE anchored to the plasma membrane G4A are involved in the cell adhesion process." (PMID 37760598, 2023). "Acute treatment of SH-SY5Y neuroblastoma cells with AChE inhibitors was found to result in increased secreted levels of sAPPα into the conditioned media of the cells." (PMID 36142659, 2022). "It has been reported that Aβ increases AchE expression in neuroblastoma cells, which in turn promotes Aβ aggregation, increasing Aβ toxicity." (PMID 36077432, 2022). "Increased intracellular cAMP levels enhance AChE expression in the neuroblastoma cell-line, Neuro-2A, affording them protection against organophosphate toxicity." (PMID 34500749, 2021). "We developed an in vitro model to measure both extracellular and intracellular ACh levels using the human cholinergic neuroblastoma cell line, LA-N-2, which have been reported to express Ch transporter, ChAT, muscarinic ACh receptor (mAChR), and AChE." (PMID 34637466, 2021). "Dioxin-mediated cell death in SK-N-SH neuroblastoma cell-line is due to decreased AChE activity mediated by an increased expression of miR-146b-5p." (PMID 34500749, 2021). "In SH‐SY5Y neuroblastoma cells expressing higher levels of P‐tau, AChE activity and protein increased by (20% ± 2%) and (440% ± 150%), respectively." (PMID 32955735, 2021). "In this study, we have investigated the interaction between AChE and P‐tau in human neuroblastoma SH‐SY5Y cells by analyzing the effect of increased tau phosphorylation mediated by GSK3β on AChE mRNA and protein expression." (PMID 32955735, 2021). "In neuroblastoma cells, application of genistein increased AChE activity and neurite outgrowth: this effect of genistein was proposed to be mediated by a tyrosine protein kinase." (PMID 29535608, 2018). "The present study in SH-SY5Y human neuroblastoma cell line aims to determine the effect of H2O2 on AChE activity and isoform profiles." (PMID 28411556, 2017). "Inflammatory cells, including eosinophils, express AChE activity, and there is evidence that eosinophils can induce AChE RNA expression and activity in a neuroblastoma cell line." (PMID 18335107, 2008). "For instance, the low surface/extracellular staining of AChE, in contrast to the high BChE staining observed in neuroblastoma cells, challenges the canonical view that AChE is the primary membrane-anchored extracellular enzyme responsible for ACh hydrolysis within synapses." (PMID 41226363, 2025). "There is evidence that ACHE overexpression or activity is detected in apoptotic cells after the induction of apoptosis by different stimuli in many different type cells, such as hematopoietic stem cells, human neuroblastoma cells, and other cell lines." (PMID 30626059, 2019).
neuroblastoma (continued). "In the present study it was hypothesized that H2O2 produces a specific effect on AChE in the human neuroblastoma SH-SY5Y cell line, modifying the levels and isoform profile of this enzyme." (PMID 28411556, 2017). "Human SH-SY5Y neuroblastoma cells, mouse C2C12 myoblast-like cells, and IMR-90 cells were fixed and stained against AChE." (PMID 41150528, 2025). "Therefore, high AChE content could affect neuroblastoma development." (PMID 37760598, 2023). "Overexpression of phosphorylated tau in the neuroblastoma cell-line, SH-SY5Y, showed increased AChE activity." (PMID 34500749, 2021). "Human neuroblastoma SH-SY5Y cells were treated with H2O2 (1–1000 μM) for 24 h and AChE activity and AChE and cytochrome c levels were evaluated." (PMID 28411556, 2017). "Similarly, surface confocal microscopy analysis validated the presence of AChE, BChE, M1-mAChR, and α7-nAChR on the surface of SH-SY5Y neuroblastoma cells." (PMID 41226363, 2025). "Studied angular coumarins were able to inhibit AChE at a low micromolar level and behaved as non-toxic compounds, showing negligible damage when co-incubated with human neuroblastoma cells." (PMID 40333852, 2025). "Treatment of the AD SH-SY5Y (human neuroblastoma cells) cell model with DPEO resulted in decreased intracellular levels of Aβ, GSK-3β, P-Tau, IL-1β, TNF-α, IL-6, COX-2, OFR, and HFR, alongside reduced AchE and BchE activities and increased SOD activity." (PMID 39056736, 2024). "The bioactive principles were identified by GC-MS and LC-MS and further subjected to antioxidant (DPPH and FRAP) and neuroprotection (AChE inhibition, ThT binding, and MTT assay, DCFH-DA and lipid peroxidation (LPO) assay using neuroblastoma (SHSY-5Y) cell lines) assays." (PMID 37234712, 2023). "The slightly lower-performing piperazine analogue 12d is instead the most interesting Aβ aggregation inhibitor (I% = 60% at 10 μM), as well as a more selective AChE inhibitor (IC50 = 0.599 μM) and shows no cytotoxic effects on neuroblastoma cell lines at 24 h at 100 μM." (PMID 36139705, 2022).